STAT3 (signal transducer and activator of transcription 3)
Diseases named in the same sentence as STAT3 in open-access papers (continued):
Sharing a sentence is not in itself a finding about the gene and the disease.
cancer (continued). "Functionally, STAT3 is considered to play a carcinogenic role in multiple malignant tumors." (PMID 35942374, 2022). "Research shows that STAT-3 is overexpressed and activated in many cancers." (PMID 35933373, 2022). "RPN2 is speculated to be involved in the progression of malignant tumours by regulating various signalling pathways, such as STAT3, NF-κB, and PI3K-Akt." (PMID 36291587, 2022). "Moreover, STAT3’s its abnormal activation together with altered IL-6 levels are often found in chronic inflammatory diseases as well as in the majority of patients suffering from cancer, making STAT3 and its pathway another attractive target in cancer therapy." (PMID 36185259, 2022). "In blood cancer, they usually fulfill cancer driver roles when hyperactivated or when their expression is enhanced, where they can also function redundantly as oncoproteins requiring dual STAT3/5 targeting modes, as for the first time explored here with direct covalent STAT3/5 degraders." (PMID 36341492, 2022). "For example, STAT3 is involved in the process of proliferation, migration and invasion of cancers." (PMID 36295083, 2022). "In addition, the regulators up- and downstream of IL6, namely, STAT3 and Toll-like receptors, respectively, have been successfully targeted in resistant cancer models." (PMID 35196078, 2022). "Targeting STAT3 is emerging as a potentially promising therapeutic modality for many cancers." (PMID 35799780, 2022). "Tumorigenicity and invasiveness are important acquired characteristics for the development and progression of cancer, and could be regulated by transcription factors associated with EMT, such as ZEB1, ZEB2, SNAI1, SLUG, and STAT3." (PMID 35723302, 2022). "In addition, the combination of DSE and DDP distinctly inhibited the phosphorylation of STAT3 in ESCC cells, which was associated with the sensitivity of DDP in cancer." (PMID 35668940, 2022). "Cancer cells grow more slowly when both AP-1 and STAT3 are downregulated." (PMID 35530318, 2022). "The multifaceted potential of STAT3 as an oncogenic transcription factor has been widely studied and recognized by its role in regulating the expression of genes related to cancer cell proliferation, invasion, migration, anti-apoptosis, immunosuppression, stem cell regeneration and autophagy." (PMID 35053592, 2022). "Additionally, pSTAT1 is surprisingly correlated with STAT3 in some cancer cell lines including breast cancer and T-LGLL." (PMID 35806366, 2022). "STAT3 is emerging as a promising target for radio-sensitization of cancer radiotherapy." (PMID 36231093, 2022). "Thus, elucidating the mechanisms of STAT3 regulation and designing inhibitors targeting the STAT3 pathway are considered promising strategies for cancer treatment." (PMID 35356799, 2022). "A well-established gene regulatory network that links IL-6-mediated chronic inflammation with cancer consists of two distinct but complementary feedback loops, one involving IL-6, NF-kB, Lin28 and let-7 miRNA, and the other comprising IL-6, NF-kB, STAT3, miR-181b-1, miR-21, CYLD and PTEN." (PMID 35757000, 2022). "It is suggested that no reduction in transporters other than ABCC2 may affect anti-cancer drug excretion in SC144-treated cells by inhibiting the gp130/STAT3 pathway." (PMID 35565185, 2022). "Indeed, activation of the JAK2/STAT3 signaling pathway has been reported in various types of cancers." (PMID 35589677, 2022). "Other classical drugs exhibited anti-cancer effects by direct or indirect targeting STAT3." (PMID 36559280, 2022). "VEGF is a downstream gene of STAT3, which promotes cancer growth and angiogenesis." (PMID 36225196, 2022). "Meanwhile, famotidine can inhibit the occurrence of cancer by inhibiting STAT3." (PMID 35743172, 2022). "However, aberrant activation of STAT3 was also found in solid and hematological cancers whereas T-cell-produced cytokines can promote STAT3 in cancer cells to impact tumorigenicity." (PMID 36613784, 2022).
cancer (continued). "Indeed, increased levels in total STAT3 have been shown to correlate with poor prognosis of advanced cancer patients." (PMID 35994202, 2022). "Therefore, IL-6 works synergistically with the TFs NF-kB and STAT3, as well as multiple miRNAs, to set up dynamic regulatory feedback loops for perpetuating inflammatory cues that promote chronic inflammation and cancer." (PMID 35757000, 2022). "Recent research indicates that the STAT3/NRF2 signaling pathway contributes to cancer progression." (PMID 36557902, 2022). "The IL-6/STAT3 signaling pathway is responsible for M2 polarization in cancer." (PMID 35193986, 2022). "Besides, other studies also provide a rationale for inhibiting STAT3 as a therapeutic target in cancer cells." (PMID 35401182, 2022). "Although the anti-inflammation and antioxidant effects of exercise are disseminated, our study is the first to demonstrate that the protective effects of RT against muscle atrophy during cancer are strictly related to its capacity to attenuate STAT3 phosphorylation and activation." (PMID 35847939, 2022). "Furthermore, outcomes from the clinical trial of combination treatment of inhibitors of the STAT3 signaling pathway with chemo- and immuno-therapy in cancer patients will better inform of further clinical utility." (PMID 35053592, 2022). "Indeed, a strict inter-connection between long-lasting/chronic inflammation and cancer onset exists, in which STAT3, NFkB and mTOR, pathways regulating both inflammation and cell proliferation, are key players." (PMID 35681760, 2022). "Additionally, IL-6-mediated activation of JAK2/STAT3 within cancer cells promotes the expression of PD-L1 and PD-L2 and checkpoint inhibition." (PMID 36700235, 2022). "After screening by integrating the sequencing results and online database, LncRNA PVT1 were chosen for further study, not only because it has been shown to have important oncogenic features in several types of cancer, but also because it was reported to interact directly with STAT3 in cancer cells." (PMID 36266267, 2022). "Importantly, STAT3 inhibitors were used in a clinical trial of patients with cancer and were generally well tolerated." (PMID 36588738, 2022). "STAT3 has been shown previously to be persistently activated in several human cancer cell lines." (PMID 35847174, 2022). "However, earlier works did not reveal the underlying mechanism of cross-talk between TrkC and DJ-1 contributing to STAT3 activation in cancer progression." (PMID 36202793, 2022). "Cancer cells need the energy to replicate, so STAT3 upregulates glycolysis to make more ATP." (PMID 35800364, 2022). "In addition, STAT3 enhances cancer cell directional migration by regulating Rac1 activity while it promotes angiogenesis by transcriptionally regulating VEGF activity." (PMID 35158821, 2022). "In addition, STAT1 and STAT3 are involved in PD-L1 expression and PD-1 checkpoint pathway in cancer by pathway analysis." (PMID 35874683, 2022). "Accordingly, STAT3 is a promising therapeutic target for the treatment of cancer." (PMID 34953855, 2022). "In addition, PKM2 can interact with transcription factors, such as HIF-1α, β-catenin/c-Myc, NF-κB and STAT3 to promote target genes transcription and enhance cancer cells growth and angiogenesis." (PMID 36471428, 2022). "Targeting STAT3 has been considered as an ideal strategy in the treatment of various cancers." (PMID 35369571, 2022). "Niclosamide inhibits Wnt/β-catenin, the mammalian target of rapamycin complex 1, signal transducer and activator of transcription 3 (STAT3), Notch signaling pathways, and nuclear factor-κB, and targets mitochondria in cancer cells to induce cell cycle arrest, growth inhibition, and apoptosis." (PMID 37529747, 2022).
cancer (continued). "STAT3 is an oncogenic transcription factor that is constitutionally activated in various human cancers and modulates various cellular functions, such as cell proliferation, survival, apoptosis, angiogenesis, immune response, and chemotherapy resistance (Tošić and Frank, 2021)." (PMID 36188586, 2022). "Finally, these data suggest that cannabigerol and IFN-γ exert their anti-cancer properties via the inhibition of STAT3 (upregulated by IL-11 and LIF) and c-Jun/AP-1 (downregulated by Pentraxin2/SAP), respectively." (PMID 36923728, 2022). "In addition to the Wnt, Shh, and TGF-β signaling pathways, research in other cancers has linked ID-1 to K-ras signaling, PI3K/Akt signaling, and STAT3 signaling, illustrating the centrality of ID-1 across multiple signaling pathways." (PMID 35954407, 2022). "This study revealed that chemoresistance in cancer cells may be mediated through STAT3/ATF6-induced autophagy." (PMID 35559037, 2022). "Finally, we address the potential therapeutic strategies against malignant tumors by targeting the signaling pathway to augment STAT3 activity." (PMID 36010693, 2022). "The JAK2/STAT3 transduction axis modulates apoptosis of cancer cells." (PMID 35288541, 2022). "Constitutive activation of STAT3 has been shown to play a crucial role in cancer progression." (PMID 36542668, 2022). "Importantly, the growth-enhancing effects of IL-6 on cancer cells also extend to cancer stem cells, capable of self-renewal and expansion, which require STAT3 to act synergistically with stem cell transcription factors such as NANOG." (PMID 36313280, 2022). "In addition, Western blot analysis showed decreased SOCS1, but increased phosphorylated STAT1 (p-STAT1)/p-STAT3 ratios in miR-155–overexpressing primary cancer cells compared with controls." (PMID 35925680, 2022). "Therefore, drugs targeting STAT3 and NF-κB, which lead to chronic inflammation, are considered an important strategy for both cancer prevention and therapy." (PMID 35890318, 2022). "The transcription factor STAT3 was also shown to promote cell viability in cancer cells." (PMID 36140293, 2022). "In general, these findings indicated that the study of new quinoxaline–aryfuran derivatives as inhibitors of STAT3 may lead to new therapeutic medical applications for cancer in the future." (PMID 36365238, 2022). "STAT3 and NF-κB act as central transcriptional hubs controlling inflammatory secretion in immune responses, and drive cancer progression and amoeboid dissemination." (PMID 36699013, 2022). "The anti-cancer activity of pyrvinium recently emerged in several models as targeting several intracellular processes including mitochondrial oxidative metabolism, and signaling such as Wnt and STAT3 signaling pathways." (PMID 35354920, 2022). "The overexpression of PBX1 could enhance the transcription of STAT3 by directly binding to its promoter, thereby promoting cancer stem cell‐like phenotypes and increasing platinum resistance in OC patients." (PMID 35068042, 2022). "Our findings should be an initial step to guide future studies by showing the interaction between STAT3 and cancer cell energy phenotype of the glycolytic pathway; which might be the underlying mechanism gain of resistance to TKI nilotinib." (PMID 36033954, 2022). "STAT3 phosphorylation is important for transcriptional activation of subsequent genes involved in proliferation and migration, and its increased levels have reported to increase proliferation in many types of cancer." (PMID 35201663, 2022). "JAK/STAT3 blockade by AG490 could significantly decrease the CCND1 protein levels to inhibit cancer cells proliferation." (PMID 35356799, 2022). "Thus, constitutive activation of STAT3 promotes angiogenesis, invasion, and metastasis of cancer cells." (PMID 35356799, 2022). "Activation of STAT3 is predictive of poor prognostic outcomes in many cancers." (PMID 36061200, 2022).
cancer (continued). "During this process, the signal transducer and activator of transcription 3 (STAT3) was not only a downstream target of interleukin-6 (IL-6) but also a part of the positive feedback loop that underlays the epigenetic switch between inflammation and cancer." (PMID 35434143, 2022). "Knocking down of p-STAT3 signaling could induce apoptosis and down-regulate matrix metalloproteinases, thus, suppressing cancer cell invasion." (PMID 35566382, 2022). "Using STAT3 inhibitors as a potential strategy in cancer therapy have attracted much attention." (PMID 34894961, 2022). "The use of natural products such as EOs that are able, on the one hand, to modulate STAT3 activation and, on the other, to induce mild oxidative stress in the highly reduced environment of cancer cells may potentially improve cancer treatment outcomes." (PMID 35956786, 2022). "STAT3 is activated constitutively in several cancers; it is a mediator of cytokines and growth factors to the nucleus, promoting invasion, metastasis, angiogenesis, survival, and proliferation in cancer cells." (PMID 35248049, 2022). "NCTD affects iron metabolism by modifying the expression of IL-6/JAK2/STAT3/hepcidin and IRP1 and suggest that the ability of NCTD to reduce tissue iron contents may be a novel mechanism associated with the anti-cancer effects of NCTD." (PMID 35735222, 2022). "The phosphorylation of STAT3 may play an essential part in regulating cancer cell growth and proliferation." (PMID 35991881, 2022). "Some studies showed that STAT3 inhibition could enhance the ICD of cancer cells induced by oncolytic Newcastle disease virus (NDV) and chemotherapy, in which STAT3 inhibition was used as an adjuvant therapy." (PMID 35665592, 2022). "As a key regulator in the anti-cancer immune response, STAT3 can be activated by various cytokines." (PMID 35628304, 2022). "In addition, CRIF1 acts as a regulator of several transcription factors such as Nur77 and STAT3 and partly determines the proliferation of cancer cells." (PMID 36263222, 2022). "We thus identify a translationally actionable approach to overcoming Kif11 inhibitor resistance that may work to block STAT3-driven resistance against other anti-cancer therapies as well." (PMID 35732128, 2022). "We next evaluated phosphorylation of STAT-3 in cancer cells on treatment with CM of activated RAW264.7 cells by western blotting and our results revealed that STAT-3 phosphorylation was elevated (3.57-fold) in 4T1 cells and the effect was abrogated on pre-treatment with Stattic (2.47-fold)." (PMID 35300689, 2022). "Studies have shown that capsaicin inhibits AP1, NF-κB, and STAT3 in cancer cells." (PMID 36428575, 2022). "Two molecules with a key role in both cancer-associated inflammatory response and immune suppression are toll-like receptor 4 (TLR4) and signal transducer and activator of transcription protein 3 (STAT3)." (PMID 35205801, 2022). "In our previous study, we showed L-PGDS overexpression could restrict cancer cell stemness and suppress the activation of STAT3." (PMID 35087591, 2022). "STAT3 is necessary for cell proliferation and survival in many cancers, including OSCC." (PMID 35562900, 2022). "Indeed, we detected increased STAT1 expression and activation, but decreased p-STAT3 levels in miR-155–overexpressing cancer cells." (PMID 35925680, 2022). "Besides inducing M2 polarization, the STAT3 pathway also upregulates PD‐L1 expression in cancer cells induced by TAMs." (PMID 35356799, 2022). "Thus, STAT3 signaling promotes the Warburg effect in cancer tissues by upregulating downstream glycolytic proteins; it also promotes cancer cell proliferation related to glycolysis through mechanisms that are not completely understood." (PMID 35356799, 2022). "In the late stages of cancer, IL-6/STAT3 may promote the gain of invasive activity and the metastatic dissemination of cancer cells by inducing epithelial–mesenchymal transition (EMT) transcription factors (EMT-TFs), such as SNAI1 and TWIST." (PMID 36010693, 2022).
cancer (continued). "STAT3 is also a downstream cellular mediator of cancer and angiogenesis, induced by IL-6 and EGFR." (PMID 36145523, 2022). "Highly expressed OLA1P2 directly binds to phosphorylated STAT3 (Tyr705) protein, which inhibits its nuclear import to a large extent, blocks the formation of phosphorylated STAT3 homodimers, and significantly affects STAT3 signaling, which inhibits the proliferation and migration of cancer cells." (PMID 35505438, 2022). "Signal transducer and activator of transcription 3 (STAT3) hyperactivation regulates immune responses in the tumor microenvironment by cytokines, growth factors, and G protein-coupled receptors to attenuate drug resistance and control cancer metastasis." (PMID 36439106, 2022). "Moreover, IL-6 drives many cancer hallmarks through the downstream activation of the STAT3 signaling pathway." (PMID 36547079, 2022). "Among transcription factors, NF-κB and STAT3 are activated in the majority of cancers and these play critical roles in mediating the link between inflammation and cancer development by activating genes that control cell survival, proliferation, invasion, and cytokine production." (PMID 35470375, 2022). "Thus, the STAT3 pathway’s complexity warrants attention when considering its roles in RT-induced protection against cancer-induced muscle atrophy." (PMID 35847939, 2022). "Although thymoquinone was introduced as a potentially effective suppressor of proliferation and angiogenesis via inhibition of STAT3, a further in vivo study may highlight thymoquinone as a potential therapeutic agent in cancers harboring active STAT3." (PMID 35267408, 2022). "As demonstrated by inhibition, IL6-dependent STAT3 signaling may involve SOCS3 upregulation in E3-ligase-dependent proteasome activation with cancer cachexia, as well as with denervation." (PMID 35626644, 2022). "Because ROS-dependent enhancement of STAT3 activation was reported in cancer cells, STAT3 may be involved in the ROS-dependent increase of c-maf expression." (PMID 35905076, 2022). "MAPK14 and STAT3 play a carcinogenic role in the research mechanism of cancer cells." (PMID 36532716, 2022). "This reveals that the STAT3 pathway is of substantial importance in cancer chemoprevention and could be a promising clinical target for liver cancer patients." (PMID 35566382, 2022). "Furthermore, the difficulties and prospects of targeting the STAT3 pathway in cancer are also discussed." (PMID 35356799, 2022). "Thus, the IL-6/JAK/STAT-3 pathway appears to regulate a majority of invasion-promoting functions in various cancer types, as well as in trophoblasts." (PMID 35625802, 2022). "Baicalein interfered with the activation of STAT3 in 4T1 cancer cells." (PMID 35955525, 2022). "Several small-molecule compounds could induce cancer cells apoptosis to exhibit anticancer properties by suppressing the STAT3 phosphorylation process, which was considered as one of the crucial targets for TNBC treatment." (PMID 35414025, 2022). "It has been investigated for the first time that, one of the possible underlying mechanisms for the re-sensitization of resistant cells to nilotinib due to targeting STAT3 might be the regulation of cell energy phenotype of cancer metabolism." (PMID 36033954, 2022). "Whether in the initial stage of malignant transformation or during the progression of cancer, STAT3 plays a crucial role in selectively inducing and maintaining the carcinogenic inflammatory microenvironment." (PMID 36591515, 2022). "IL-6/JAK2/STAT3 signaling pathway deserves attention in the treatment of human cancer." (PMID 36591515, 2022). "Finally, we discuss potential therapeutic strategies for cancer that target the signaling pathway to augment STAT3 activity." (PMID 36010693, 2022). "Therefore, STAT3 molecular signaling pathways can be considered a downstream target for cancer therapy." (PMID 35566382, 2022).